CD4 (CD4 molecule)
Diseases named in the same sentence as CD4 in open-access papers (continued):
Sharing a sentence is not in itself a finding about the gene and the disease.
gonorrhea (10 papers, 2012 to 2025). A common sexually transmitted bacterial infection caused by Neisseria gonorrhoeae. "The encouraging data demonstrated that this novel gonorrhea skin patch induced significant adaptive cellular immunity i.e., antigen-specific CD4 and CD8 lymphocytes." (PMID 30181504, 2018). "Phase variable Opa protein-dependent binding to CEACAM1 expressed by DCs can also effectively suppress their maturation in response to activating stimuli including gonococcal infection, preventing the cells from stimulating both CD4+ T cell and CD8+ T cell responses." (PMID 32582133, 2020). "Also, although compared with HIV mono-infected, the mean of CD4+lymphocyte was higher among gonorrhea infected patients (368±238 vs. 415±328, respectively), but the difference was not significant." (PMID 30510656, 2018). "Also, the mean of CD4+lymphocyte was higher among gonorrhea infected patients (368±238 vs. 415±328)." (PMID 30510656, 2018). "The Opa-CEACAM1 dependent effects on DC and T cell effector function would presumably contribute to the absence of effective adaptive memory responses in response to gonorrhea, impacting CD4+ T cells’ role in the adaptive response and CD8+ T cell-mediated killing of N. gonorrhoeae infected cells." (PMID 23424672, 2013). "This novel gonorrhea vaccine skin patch is tested in vivo using mouse model and data demonstrated that transdermal vaccine delivery induced significantly higher levels of humoral and adaptive immune responses i.e., antigen-specific serum IgG and antigen-specific CD4 and CD8 T lymphocytes." (PMID 30181504, 2018). "Heptose phosphates therefore provide a direct link between gonococcal infection and HIV-1 replication in CD4+ T cells by the virtue of NF-κB activation through TIFA-AlpK1 axis." (PMID 32582133, 2020). "We have repeatedly found that genital gonococcal infection in mice induces the generation of Th17 responses as shown by the production of IL-17 by CD4+ T cells, regardless of any treatment (8, 30; this study)." (PMID 29404418, 2018). "While the numbers are smaller, it is notable that there is a significant increase in endocervical CD4+, CD8+, and γδ T cells during uncomplicated gonococcal infection regardless of whether cervicitis is apparent or not." (PMID 32582133, 2020). "CD4 T cell levels were not significantly different between PBS and gonococcal-treated mice, supporting a compartmentalization of the mucosal response to gonorrhea." (PMID 29360873, 2018).
hearing loss (10 papers, 2015 to 2025). "An increased number of CD4 T cells had increased odds of developing hearing loss the current cohort." (PMID 38566657, 2024). "More recently, studies using the murine model have demonstrated LF-associated SNHL occurs in a CD4 T cell-dependent manner, with depletion of CD4 T cells preventing hearing loss." (PMID 38400041, 2024). "To assess the relationship between T-cells and LASV-induced hearing loss, we performed a T-cell depletion study using anti-CD4 and/or CD8 monoclonal antibody (mAb) injection." (PMID 35605008, 2022). "CD4 T cell depletion is sufficient to prevent the development of hearing loss, indicating its role as the driving factor of SNHL." (PMID 36289695, 2022). "The prevalence of hearing loss was lower than expected, so the study was underpowered for some responses, such as CD4<200." (PMID 27551970, 2016). "Given that participants with higher CD4 cell count were the ones with an increased risk for hearing loss, this could be due to the possible ototoxic nature of the ART alluded by Khoza-Shangase." (PMID 38566657, 2024). "However, age, extended use of ART, increased number of CD4 cell and some comorbidities were found to be significantly associated with hearing loss in this cohort." (PMID 38566657, 2024). "However, Torre and colleagues found race to be one of the potential risk factors for hearing loss in adults living with HIV, while Obasineke and colleagues found CD4 cell count to be a risk factor for hearing loss in adult population." (PMID 38566657, 2024). "Few studies have made connections between hearing loss and the number of CD4 cells." (PMID 38566657, 2024). "Current findings have indicated that hearing loss in adults living with HIV is common, and ageing, male, other comorbidities, increased number of CD4 cell counts, and extended use of ART increase the risk for hearing loss." (PMID 38566657, 2024). "Current WHO Stage, and current or nadir CD4 <200 were not related to hearing impairment." (PMID 27551970, 2016).
hemophilia (10 papers, 2013 to 2024). Hemophilia is a genetic disorder characterized by spontaneous hemorrhage or prolonged bleeding due to factor VIII or IX deficiency. "For optimal patient care outcomes, factors including CD4 count, nutritional status, adherence to cART, viral load, and other conditions like hemophilia or infections from intravenous drug use must be considered when managing PLWHIV." (PMID 38790936, 2024). "Employing murine models of the inherited bleeding disorder hemophilia, we find that oral antigen administration induces three CD4+ Treg subsets, namely FoxP3+LAP-, FoxP3+LAP+, and FoxP3-LAP+." (PMID 37954612, 2023). "In hemophilia trials for example it was found that IM injection into skeletal muscle resulted in transient therapeutic gene expression and an adaptive CD4+ immune response." (PMID 24934216, 2014). "Decline seems to be proportional with the decrease of immunological functioning, especially when the CD4+ cell counts ≤200, even though other studies have concluded that the decline is related to hemophilia per se." (PMID 25009488, 2014). "To this aim, we isolated Tregs (CD4+CD25+) and effector T cells (CD4+CD25−) 3 weeks after administration of LV-FIX to pre-immunized haemophilia B mice (n = 3), when anti-FIX Abs were already reduced compared to saline-injected mice." (PMID 24106222, 2013). "Furthermore, low CD4+/CD8+ cell ratio are usually related to acute viral diseases and hemophilia, whereas high ratios are observed individually with stimulation of immuno-functional ability." (PMID 26008237, 2015). "Among these patients, 81 were excluded from this investigation; 4 of these patients had hemophilia and we could not confirm the reason for HIV testing for 23 patients, CD4 counts for 44 patients, or an accurate age at the time of HIV diagnosis for 10 patients." (PMID 26934235, 2016).
immunotoxicity (10 papers, 2014 to 2024). "We showed that chronic arsenic exposure from drinking water is related to changes in the transcriptome and methylome of CD4-positive T cells, both genome wide and for specific genes, supporting the hypothesis that arsenic causes immunotoxicity by interfering with gene expression and gene regulation." (PMID 27838757, 2017). "In conclusion, chronic arsenic exposure from drinking water was related to changes in the transcriptome and methylome of CD4-positive T cells, both genome wide and in specific genes, supporting the hypothesis that arsenic causes immunotoxicity by interfering with gene expression and regulation." (PMID 27838757, 2017). "In a study, copper-treated mice exhibited ROS production and changes in the mitochondrial transmembrane potential, mainly leading to immunotoxicity in the form of reduced CD4+ T-cell populations and increased or proliferating CD4+ T-cell populations." (PMID 36387247, 2022). "In the study of immunotoxicity, Tl (I) suppresses the expression of genes involved in B cell development, enhances the production of thymic CD4+ T cells, and promotes the migration of initial CD4+ T cells and recent thymic emigrants (RTE) from the thymus to the spleen." (PMID 38731969, 2024). "In mice, Cd treatment resulted in dose- and time-dependent accumulations of Cd in CD4+ cells and dose- and time-dependent decreases in the CD4+/CD8+ ratio, which is a bio-indicator of immunotoxicity." (PMID 34354707, 2021). "On the one hand, we found no significant changes in indicators of immunotoxicity, including IgG, IgM, complement C3, C4, CD4+, and CD8+ T-cell subsets, in the present study." (PMID 38020919, 2023). "Alterations in the CD4+ and CD8+ profiles could reflect changes in the overall condition of the immune system due to immunotoxicity." (PMID 25099245, 2014). "Our results demonstrated that OsrHSA is equivalent to pHSA in terms of its effects on T cell proliferation, CD4+ and CD8+ T cells and cytokine levels, suggesting that there is no evident potential for immunotoxicity with OsrHSA treatment in PBMC." (PMID 25099245, 2014).
insomnia (10 papers, 2014 to 2025). A sleep disorder characterized by difficulty in falling asleep and/or remaining asleep. "There were also moderate correlations between CD4 at baseline and CD4 at three months, respectively, and insomnia at three months." (PMID 37936126, 2023). "Higher levels of CCL23, CD4, Gal-1 and MMP7 at baseline were all strongly associated with insomnia at EOT." (PMID 37936126, 2023). "In addition, a cross-sectional study conducted in France found that patients with CD4 count <500 cells/mm3 were more likely to be long sleepers and less likely to experience insomnia." (PMID 34295273, 2021). "Joyce (aged 60) who was not yet on ART (because her CD4+ cell count was high) but on Cotrimoxazole, reported physical pains ‘constantly attacking’ her, preventing enjoyment of life and causing insomnia." (PMID 25053275, 2014). "In this study, high levels of four inflammatory proteins; CCL23, CD4, Gal-1, and MMP7, at baseline correlated strongly with insomnia at EOT." (PMID 37936126, 2023). "Sleep latency was associated with differences in CD8+ T cell counts; however, this relationship was not robust as differences in the CD4+/CD8+ T cell ratio were not seen and other measures of insomnia did not appear to be related to T lymphocyte counts." (PMID 38420256, 2024).
latent syphilis (10 papers, 2013 to 2025). A stage of syphilis characterized by the serologic evidence of infection by Treponema pallidum without evidence of accompanying signs or symptoms related to the disease. "Peripheral blood samples from 30 HCs, 24 secondary syphilis infection patients and 41 latent syphilis patients were analyzed by flow cytometry, and CD4+CXCR5+CD25lowCD127intermediate-highTfh cells were identified." (PMID 37901207, 2023). "The third vignette described a patient with early latent syphilis with a CD4+ cell count above 350 cell/mm3 and a VDRL titer of 1:128 with a four-fold (two dilution) decrease in the titer within 12 months after adequate treatment." (PMID 36043668, 2023). "Most participants believe that the criteria for lumbar puncture should be extended; almost 60% believe that low CD4+ cell counts should be an indication, and around a third favor late latent syphilis as a criterion to proceed with lumbar puncture even in asymptomatic patients." (PMID 36043668, 2023). "A 28-year-old transgender male to female with a history of untreated HIV (CD4 count = 175 cells/μL, HIV RNA = 221,000 copies/mL), latent syphilis, and methamphetamine use disorder presented to the emergency department with a five-month history of progressive left foot pain, ulceration, and swelling." (PMID 40161061, 2025). "Here, we present the case of a 28-year-old homeless transgender female with untreated HIV (CD4 count = 175 cells/μL, HIV RNA = 221,000 copies/mL), latent syphilis, and methamphetamine use disorder, who presented with a five-month history of progressive left foot pain, ulceration, and swelling." (PMID 40161061, 2025). "Patient 3 was diagnosed with late latent syphilis of unknown duration and HIV-2 concurrently (HIV-2 RNA 13 copies, CD4 109 cells/mm3)." (PMID 38464490, 2024).
Lewis lung carcinoma (10 papers, 1997 to 2026). "Moreover, ectopic POPDC3 overexpression in C57BL/6 J mouse Lewis lung carcinoma (LLC) xenografts enhanced CD4+ T cell infiltration and PD-1 expression in the TME." (PMID 39971925, 2025). "On the other hand, in Lewis lung carcinoma model, the central memory T cells (CD44highCD62Lhigh in CD4+ or CD8+) have been quantified, which suggests that FeMOF-based cancer vaccines may enhance immune memory." (PMID 38259474, 2023). "In the Lewis lung carcinoma model, vaccination efficiently increases the CD3+CD4+ and CD3+CD8+ T cell populations in the spleens and CD3+CD8+, CD3−CD8+, and CD11b+CD80+ cell populations in the tumors, suggesting the alteration of tumor microenvironments from cold to hot tumors." (PMID 38932378, 2024). "In the Lewis lung carcinoma model, vaccination efficiently increases the CD3+CD4+ and CD3+CD8+ T cell populations in the spleens and CD3+CD8+, CD3−CD8+, and CD11b+CD80+ cell populations in the tumors, suggesting the alteration of the tumor microenvironment from cold to hot tumors." (PMID 38932378, 2024). "Heat stressed EVs (HS-EVs).HS-EVs chemoattracted CD11+ DCs and CD4+/CD8+ T cells in vitro and in vivo.In vivo3LL Lewis lung carcinoma modelIT injection of HS-EVs induced more efficient specific antitumour response in comparison with EVs - ↓ tumour growth, ↑ survival." (PMID 31680949, 2019).
Löfgren's syndrome (10 papers, 2009 to 2020). "Additionally, HLA-DR3-expressing Löfgren's syndrome patients exhibit oligoclonal expansions of CD4+ T cells in the BAL that express TCRα variable region (TRAV) 12-1, and the quantity of these cells in the BAL correlates with disease remission." (PMID 32256501, 2020). "Using deep sequencing approaches, our group recently demonstrated that TRAV12-1 preferentially pairs with TCRβ variable region (TRBV) 2 in BAL CD4+ T cells from Löfgren's syndrome patients and that TRAV12-1 and TRBV2 are the most expanded variable regions relative to control subjects." (PMID 32256501, 2020). "Compared to a distinct subgroup of patients i.e. those with Löfgren's syndrome, BALF CD4+ T cells from non- Löfgren's patients expressed decreased mRNA levels of TIM-1 (p < 0.05)." (PMID 19480659, 2009).
mucormycosis (10 papers, 2013 to 2025). "We should assess the patient’s immune status (e.g., PD-1 expression levels on CD4+ and CD8+ T cells) before initiating anti-PD-1 treatment and regularly monitor immune status to provide stronger evidence for the efficacy of ICIs in treating mucormycosis." (PMID 40672833, 2025). "However, T-cells such as CD4+ and CD8+ are seen explicitly in invasive mucormycosis and have been suggested as a possible non-invasive diagnostic test for mucormycosis." (PMID 35806905, 2022).
osteomyelitis (10 papers, 2010 to 2026). An acute or chronic inflammation of the bone and its structures due to infection with pyogenic bacteria. "To assess activation of T cells we determined these receptors on CD4+ T cells of patients with implant-associated osteomyelitis immediately before surgery." (PMID 21151520, 2010). "Conversely, reduced CD3 signaling strength in TD CD4+ T cells linked to protection against osteomyelitis suggests that dampening naïve T cell responsiveness could alleviate inflammation." (PMID 38650858, 2024). "HIV-induced depletion of CD4+ T cells compromises the body’s ability to fight infections effectively, making HIV patients more susceptible to osteomyelitis." (PMID 41497025, 2026). "Anti-CXCL4 (PF4) antibody was found to inhibit the percentage of Tregs, while the recombinant CXCL4 protein increased the percentage of Tregs in the CD4+ T in chronic osteomyelitis." (PMID 40114921, 2025). "MAC osteomyelitis is notoriously known to affect the vertebrae, frequently seen in patients with reconstituted CD4 counts following the initiation of ART therapy." (PMID 36381873, 2022). "It is essential to recognize MAC as a potential cause of osteomyelitis in patients with HIV, even if CD4 counts are above 50 cells/mm3." (PMID 36381873, 2022). "Previous studies have reported that STAT5/CD4+CD25+FOXP3 Tregs pathway plays a critical role in the pathogenesis of chronic osteomyelitis and acute ischemic stroke." (PMID 36162982, 2022). "During osteomyelitis, an increased number of CD4+CD28- T lymphocytes was observed in bone tissue, which was associated with long-term activated T cells, CD11b overexpression, and enhanced cytotoxic ability, all characteristics of T-cell senescence." (PMID 34341698, 2021). "An increased risk of osteoarticular infections such as septic arthritis, prosthetic infections, osteomyelitis has been shown to increase if the CD4 count is < 200–400 cells/mm3." (PMID 31672149, 2019). "Elevations in circulating CD4+ T cells, potentially enriching Th1 and Th17 proinflammatory subsets, as well as increases in HLA-DR+ CD4+ and CD8+ T cells indicative of activation were linked to higher osteomyelitis risk." (PMID 38650858, 2024). "In the Treg cell group, CD127 on CD4+ (p = 0.031, OR = 0.654, 95%CI = 0.445–0.962) showed a negative causal relationship with the development of osteomyelitis." (PMID 38650858, 2024). "MAC osteomyelitis may be an underdiagnosed condition in patients with HIV who are on ART with adequate CD4 counts." (PMID 36381873, 2022). "Additionally, this study underscores the underrecognition of MAC osteomyelitis in HIV and should remain high on differential diagnoses, despite adequate CD4+ count and ART therapy." (PMID 36381873, 2022).
pericardial effusion (10 papers, 2011 to 2024). Fluid collection within the pericardial sac, usually due to inflammation. "Patients with lower CD4 count levels would be at higher risk of severe pericardial effusion." (PMID 36751245, 2023). "Patients with a lower CD4 count were noted to be at higher risk of pericardial effusion." (PMID 36751245, 2023). "Pericardial effusion is a late manifestation of HIV more commonly observed in individuals with depressed CD4 counts." (PMID 36153612, 2022). "In the case of pericardial effusion, heart biopsies show infiltration of T-lymphocytes, mostly CD4+." (PMID 36079112, 2022). "Independent predictors of a small pericardial effusion were higher resting pulse rate (OR 1.051, 95% CI: 1.013–1.090, p = 0.009), low CD4 cell count (OR 0.996, 95% CI: 0.993–0.999, p = 0.004) and high WBC count (OR 1.280, 95% CI: 1.044–1.570, p = 0.018)." (PMID 22331234, 2012). "In patients with pericardial effusion, 39 had mild effusion while eight had moderate to severe effusion, with a mean CD4 cell count of 125/μl." (PMID 22907266, 2012). "Pericardial effusions are generally lymphocytic with CD4+ T cells dominating in HIV-1 uninfected and CD8+ T cells in HIV-1-infected pericardial TB patients." (PMID 22215422, 2012). "Pericardial effusions have been found to be up to three times more likely, venous thromboembolism two to ten times more likely (especially if the CD4+ T cell count is low), and sudden cardiac death twice as likely in PLWH compared to their healthy counterparts." (PMID 36573732, 2022). "Pericardial effusion: in a model of age, gender, HIV duration, CD4 cell count, pulse rate, haemoglobin level and WBC count, younger age was independently associated with a diagnosis of having a large pericardial effusion (OR 0.890, 95% CI: 0.792–0.999, p = 0.049)." (PMID 22331234, 2012). "Patients with small pericardial effusions were also generally sick, as evidenced by the presence of tachycardia, high WBC count, high serum creatinine levels and low CD4 cell count." (PMID 22331234, 2012). "HIV-infected patients with pericardial effusions generally have lower CD4 counts than those without effusions." (PMID 23782480, 2013).